CP (ceruloplasmin)
Diseases named in the same sentence as CP in open-access papers (continued):
Sharing a sentence is not in itself a finding about the gene and the disease.
pancreatic cancer (13 papers, 2008 to 2024). "AGR2, POSTN, TFF1, and CP were selected because their transcribed proteins have been previously implicated as potential biomarkers for pancreatic cancer." (PMID 36812168, 2023). "The results revealed that the embryos transplanted into pancreatic cancer PANC-1 cells treated with CP-FaP2 or CP-FaP3 showed much less tumor progression than the embryos treated with the control peptides." (PMID 36797256, 2023). "Since CP is involved in angiogenesis and neovascularisation of cancer, CP should be a key gene in tumor-stroma crosstalk of pancreatic cancer." (PMID 30519576, 2018). "Pancreatic cancer cells can result in the synthesis of increased sLex on CP found in patients with pancreatic cancer." (PMID 30519576, 2018). "Our results showed that adhesion to type 1 collagen and migration through this ECM protein is dependent on α2β1 integrin in CP and C31 cells, which is in agreement with other reports in pancreatic cancer cell lines." (PMID 24878505, 2014). "Genes which detoxify superoxide (superoxide dismutases 2 and 3) and which prevent the generation of hydroxyl radical (ferroxidase/ceruloplasmin) were upregulated in SU86.86 pancreatic cancer cells through Mirk." (PMID 24281169, 2010). "Using a statistical bootstrap approach, they showed that three large-mass proteins involved in inflammatory responses were elevated in pancreatic cancer sera: α-2 macroglobulin, ceruloplasmin and complement 3C." (PMID 20588270, 2010). "Furthermore, we tested the role of CP-FaP2 and CP-FaP3 in malignant pancreatic cancer by using a zebrafish embryo xenograft model, in which injected fluorescence-labeled tumor cells can metastasize into the tail fins." (PMID 36797256, 2023). "For inhibiting the proliferation of pancreatic cancer cells, Mito-CP and a synthetic cationic acetamide analog (Mito-CP-Ac) suppressed cellular energy metabolism function, activated AMPK energy-sensing pathway, and changed the roles of glycolysis and citrate in mitochondrial bioenergy metabolism." (PMID 37954849, 2023). "Furthermore, results of the wound healing migration, transwell migration, and matrigel invasion assays revealed that CP-FaP2 and CP-FaP3 significantly reduced the motility of pancreatic cancer cells." (PMID 36797256, 2023). "Several factors of the CSC secretome have been proposed as biomarkers, like ceruloplasmin identified in pancreatic cancer, which could be used in addition to CA19-9." (PMID 33059744, 2020). "E-cadherin could be a candidate mediator of the effect of Fgf in the CPe, as it is expressed in adult CP and Fgf treatment can upregulate E-cadherin expression in pancreatic cancer cell lines." (PMID 19114013, 2008). "Indeed, the chimeric peptide CP-FaP2 or CP-FaP3 interferes with the formation of the FAM83A-β-catenin and β-TCF4 complex, decreasing the stability of β-catenin, and counteracts the oncogenic capability of pancreatic cancer cells in vitro and in vivo." (PMID 36797256, 2023). "Among them, positive (i.e., serum amyloid A, ceruloplasmin, complement factors, haptoglobin) and negative acute-phase reactants (i.e., transthyretin, transferrin) were differentially expressed in sera from ovary, lung, liver, and pancreatic cancer patients." (PMID 23401773, 2013).
Parkinsonism (13 papers, 2013 to 2026). Characteristic neurologic anomaly resulting from degeneration of dopamine-generating cells in the substantia nigra, a region of the midbrain, characterized clinically by shaking, rigidity, slowness of movement and difficulty with walking and gait. "Researchers observed a loss of approximately 80% of the ferroxidase activity of CP in the SN of PD cases; CP−/− mice developed parkinsonism and exhibited iron accumulation in the SN." (PMID 37372019, 2023). "Several point mutations in the CP-encoding gene are significantly associated with PD and Parkinsonism, indicating that CP-mediated iron homeostasis is also likely involved in PD pathogenesis." (PMID 36674772, 2023).
colon carcinoma (12 papers, 2012 to 2024). "In particular, it has been demonstrated that, on colon cancer cells, the antiproliferative activity of CP is associated to functional suppression of the ubiquitin-proteasome pathway and to the induction of ER stress." (PMID 24980813, 2014). "In conclusion, CP can potentially be a new therapeutic tool to selectively kill colon cancer cells by paraptosis action." (PMID 37259382, 2023). "Research on rats indicated that low intake of Cu is a risk factor for the development of colon tumor, induced by 3,2′-dimethyl-4-aminobiphenyl and reduced the activities of Cu,Zn-superoxide dismutase (SOD) and ceruloplasmin." (PMID 35433131, 2022). "It is believed that the present data represents the first evidence of CP-LAAO cytotoxic activity in human colon cancer cells." (PMID 29890640, 2018). "Differently from what assessed in colon cancer cells, ER stress induced by CP triggered a caspase-dependent apoptotic program." (PMID 24980813, 2014). "The cytotoxic effect of CP in colon cancer cells has been correlated to the induction of a programmed non-apototic mechanism of cell death, called paraptosis or type III cell death." (PMID 24980813, 2014). "Additionally, the expressions of SPARCL1, CP and TF differed significantly between stage IV colon cancer and normal (p < 0.05), while that of SPARCL1, CDH2, CP and SERPINA5 differed significantly between rectum adenocarcinoma and normal tissues." (PMID 34422629, 2021). "High CP expression was also found in other cancer cells, such as breast and colon carcinoma." (PMID 32708433, 2020). "Differently from colon cancer cells, where the activation of ER stress by CP led to paraptosis, in B-lymphoblastic leukemia cells it triggered a caspase-dependent apoptosis as demonstrated by the significant increase of cell viability in the presence of the pancaspase inhibitor z-VAD.fmk." (PMID 24980813, 2014). "Previous observations indicated that in colon cancer cells CP may induce functional suppression of the ubiquitin–proteasome pathway inhibiting all the proteolytic activity of the proteasome." (PMID 24980813, 2014). "Moreover, experiments in animals indicated that low Cu intake is considered as a risk factor for 3,2’-dimethyl-4-aminobiphenyl (DMABP)-induced colon tumor development in rats, whereas the activities of ceruloplasmin and Cu,Zn-SOD enzymes were reduced in rats fed on low Cu intake." (PMID 33680379, 2020). "Interestingly, CP-PIC showed better antitumor activity in SW620 colon cancer cells under hypoxia than under normoxia, since it may be applied to chemoresistance." (PMID 23589723, 2013). "Ceruloplasmin is a direct target of SARI (basic leucine zipper ATF-like transcription factor 2) in dextran sodium sulfate (DSS)- and azoxymethane (AOM)-induced colon cancer." (PMID 34413268, 2021).
melanoma (12 papers, 2019 to 2025). A malignant, usually aggressive tumor composed of atypical, neoplastic melanocytes. "S100A4 and ITGAV displayed dataset-specific patterns: negatively associated with SC and CP in metastatic melanomas, but positively with MHC and EC in primary ones." (PMID 40943183, 2025). "Accordingly, the depletion of CP in B16-F1 melanoma cells was previously shown to cause an explosive formation of filopodia." (PMID 36980231, 2023). "In this work, we examined the consequences of CP loss in mouse B16-F1 melanoma cells and NIH 3T3 fibroblasts." (PMID 36980231, 2023). "In agreement with previous work analyzing CP-depleted Dictyostelium or B16-F10 mouse melanoma cells, elimination of CP in B16-F1 cells caused a significant increase in F-actin intensity, as evidenced by epifluorescence imaging of phalloidin-stained wild-type and mutant cells at identical settings." (PMID 36980231, 2023). "To test the hypothesis of whether Ena/VASP proteins are essential for filopodia formation in CP-deficient cells, we first disrupted the single gene (CapZb) encoding the ß-subunit of CP in B16-F1 mouse melanoma cells using CRISPR/Cas9 technology." (PMID 36980231, 2023). "This indicated that the mutation of ZEB1 may influence OS of melanoma patients and mutation of CP may be related to tumor progression." (PMID 35232428, 2022). "It showed that the mutation of ZEB1 could cause a significant decrease in the OS in melanoma patients, and mutation of CP was closely related to the progression of the tumor." (PMID 35232428, 2022). "In TISIDB database, surprisingly, we found that among all known tumors, the high expression of CP only showed a longer survival time in melanoma patients." (PMID 35232428, 2022). "It showed that the mutation of ZEB1 would lead to shorter OS in patients with melanoma (P < 0.001), while the progression survival time (PFS) of patients with the mutation of CP was significantly decreased (P < 0.05)." (PMID 35232428, 2022). "In our study, the expression level of CP in melanoma is presumably decreased in tumor tissues and the PFS of melanoma patients with CP mutation is significantly reduced." (PMID 35232428, 2022). "Using the cBioPortal database, we analyzed the genetic alternations of ZEB1 and CP in 1516 samples from 1477 melanoma and skin melanoma patients." (PMID 35232428, 2022). "High levels of ceruloplasmin expression have been defined in various cancers, such as thyroid carcinoma, melanoma, and kidney cancer." (PMID 34679534, 2021). "Since these differences are certainly even more pronounced in diverse cell types such as the B16-F1 melanoma cells and NIH 3T3 fibroblasts used here, the specific phenotype that emerges after the loss of CP in one cell type cannot simply be transferred to the other." (PMID 36980231, 2023). "ZEB1 and CP were altered in 10% and 7% of the queried melanoma samples, respectively." (PMID 35232428, 2022). "Next, we discussed the immune infiltration level of ZEB1 and CP in melanoma." (PMID 35232428, 2022). "Because these genes were lowed-expressed in melanoma tissues, but Hazard ratio of CS and SQLE were on the right side of 1 in the forest map, we selected CP and ZEB1 for the next analysis." (PMID 35232428, 2022).
melanoma (continued). "More importantly, we find that CP and ZEB1 have special effects in melanoma, which also provides a new insight for future research exploring molecular mechanism and drug treatment in melanoma." (PMID 35232428, 2022). "The isobol curve and CI plot revealed a typical synergistic interaction between DET and CP with the CI of <1, thereby suggesting that DET sensitized CP in inhibiting melanoma cells." (PMID 31736746, 2019). "In this study, we found six mitochondria-related genes, BTG2, CP, LRIG1, CYP1A1, GBP2, and MBNL1, which might be targets of quercetin in melanoma and play crucial roles in melanoma." (PMID 37869567, 2023). "Then we drew the K–M curves of CP in relation with OS and DFS in melanoma patients." (PMID 35232428, 2022). "Then we discovered and analyzed the effects of CP and ZEB1 in melanoma patients." (PMID 35232428, 2022). "C1q further induces proliferation, migration and murine melanoma cell adhesion, corroborating the hypothesis that C1q promotes melanoma progression in vivo independent of the CP activation." (PMID 40370471, 2025). "Combining the results of RNA-seq, molecular docking, and bioinformatics analysis, we found six mitochondria-related genes, BTG2, CP, LRIG1, CYP1A1, GBP2, and MBNL1, which might be targets of quercetin in melanoma and provide an available targeting therapy strategy for melanoma." (PMID 37869567, 2023). "However, the study of CP in melanoma tumors has not been fully conducted, which provides ideas for the next research." (PMID 35232428, 2022).
epilepsy (11 papers, 2017 to 2024). A brain disorder characterized by episodes of abnormally increased neuronal discharge resulting in transient episodes of sensory or motor neurological dysfunction, or psychic dysfunction. "Thus, activation of GABAergic neurons expressing CP-AMPA receptors may underlie the hyperexcitation of glutamatergic neurons in epilepsy." (PMID 38577639, 2024). "Thus, we postulated that vezatin plays a role in regulating CP-AMPARs that underlies epilepsy." (PMID 34642320, 2021). "We describe a 7-month-old female patient with severe intellectual disability, epilepsy, and low levels of serum copper and ceruloplasmin." (PMID 38172222, 2024). "CFH and ceruloplasmin were only detected in the plasma of dogs with epilepsy, suggesting potential roles in neuroinflammation and seizures." (PMID 38192726, 2023). "The plasma proteomic pattern was assessed, and five major proteins potentially involved in the pathogenesis of epilepsy and elevated Aβ levels were identified: haptoglobin (HP), α2-macroglobulin, ceruloplasmin, complement factor H (CFH), and gelsolin." (PMID 38192726, 2023). "Complement factor H and ceruloplasmin were only detected in epilepsy dogs, suggesting that neuroinflammation plays a role in epileptic seizures." (PMID 38192726, 2023). "The plasma proteomic pattern was identified, and five major proteins potentially involved in the pathogenesis of epilepsy and control of Aβ levels, including HP, α2-macroglobulin, ceruloplasmin, CFH, and gelsolin, were identified." (PMID 38192726, 2023). "The findings suggested that haptoglobin, ceruloplasmin, α2-macroglobulin, complement factor H, and gelsolin play roles in canine epilepsy and Aβ levels based on proteomic profiling." (PMID 38192726, 2023). "AMPA-type glutamate receptors in the CNS are normally impermeable to Ca2+, but the aberrant expression of Ca2+-permeable AMPA receptors (CP-AMPARs) occurs in pathological conditions such as ischemia or epilepsy, or degenerative diseases such as ALS." (PMID 32792936, 2020). "The authors’ previous study demonstrated that in the pilocarpine model of epilepsy, the incorporation of CP-AMPARs in the excitatory synapses of cortical pyramidal neurons occurs 3 days after SE." (PMID 30618633, 2018). "In the present study, ceruloplasmin was only detected in dogs with epilepsy." (PMID 38192726, 2023). "The relationship between epilepsy and partial duplication of the ceruloplasmin gene in mice in epilepsy, which is coinherited with seizures, was studied, and duplication of the gene was associated with increased ceruloplasmin mRNA expression and ceruloplasmin oxidase activity." (PMID 38192726, 2023). "One of the mechanisms of increased CP-AMPARs in epilepsy is the silencing of GluA2 transcription." (PMID 34483848, 2021). "Recent studies identified that CP-AMPARs may contribute to neural dysfunction and the related excitotoxicity in epilepsy." (PMID 34483848, 2021). "In summary, NBP had an anticonvulsant effect in an in vivo PTZ-induced epileptic seizure model, reduced epileptiform activity in the CA1 region of hippocampal slices in an in vitro 4-AP epilepsy model, and selectively regulated the AMPA current through postsynaptic CP-AMPARs." (PMID 29228686, 2017). "However, children with epilepsy displayed significantly higher concentrations of serum Zn and slightly elevated Cu in comparison to the paediatric patients without epilepsy, whereas serum CP concentrations were not statistically different between the groups." (PMID 35745104, 2022).
iron overload (11 papers, 2010 to 2025). "Hereditary aceruloplasminemia is a genetic disease characterized by progressive iron overload (liver and brain) and is related to mutations in the ceruloplasmin (CP) gene." (PMID 33959146, 2021). "Iron overload in the CNS is very likely linked to the loss of GPI-ceruloplasmin from astrocytes, which deregulates brain iron traffic." (PMID 30420953, 2018). "Lower ceruloplasmin activity in PD may be associated with iron overload in SN." (PMID 25943368, 2015). "In TDT, chronic transfusions and resulting iron overload can lead to a dysregulation of CP function." (PMID 40421055, 2025). "Mutations of HFE, hemojuvenil, hepcidin, transferrin receptor 2 (TfR2), Ireg1, transferrin, ceruloplasmin and ferritin all lead to some form of iron overload." (PMID 27363994, 2016). "Diagnosis typically relies on the detection of extremely low or undetectable serum ceruloplasmin levels, along with clinical, biochemical, and radiological evidence of iron overload in target organs, and is confirmed by genetic testing to identify mutations in the CP gene." (PMID 39165621, 2024). "Patients with aceruplasminemia are completely protein deficient for CP mutations on chromosome 3, and these patients present symptoms of iron overload (CP is ferroxidase) rather than copper accumulation." (PMID 37296680, 2023). "The proportion of liver iron overload, indicated by positive hepatic Perl's staining, in NAFLD patients with low CP ratio was significantly greater than that in those with high CP ratio (44.9% vs. 15.9%, p < 0.001)." (PMID 35795637, 2022). "Studies have shown that CP levels are often decreased in TDT patients, which may contribute to the development of complications such as iron overload and oxidative stress." (PMID 40421055, 2025). "The present study enrolled biopsy-proven patients with NAFLD without T2DM and showed that the CP ratio was inversely correlated to the histological severity of NAFLD, the presence of NASH, and hepatic iron overload." (PMID 35795637, 2022).
ischemia (11 papers, 2012 to 2021). A hypoperfusion of the BLOOD through an organ or tissue caused by a PATHOLOGIC CONSTRICTION or obstruction of its BLOOD VESSELS, or an absence of BLOOD CIRCULATION. "The CP-Tg mice showed initial ischemia for the first 10 minutes, followed by rapidly reperfusion to almost normal blood flow at 25–30 mins during AA (10 mg/kg) induction." (PMID 29374184, 2018). "Hippocampal neurons have been reported to exhibit internalization of CI-AMPARs, and translocation of CP-AMPARs to the synaptic membrane is facilitated in these neurons; therefore, these mechanisms may be relevant to ischemia-induced neuronal injury and death." (PMID 33391143, 2020). "Furthermore, we hypothesize that the ability of targeting both CP and LP activation may be especially beneficial in multifactorial pathologies where both pathways are involved in driving tissue damage, such as ischemia/reperfusion injuries." (PMID 30210498, 2018). "The inserted GluA2-lacking CP-AMPARs may be relevant to ischemia-induced synaptic remodeling and neuronal death." (PMID 34483848, 2021).